BRCA1 (BRCA1 DNA repair associated)
Diseases named in the same sentence as BRCA1 in open-access papers (continued):
Sharing a sentence is not in itself a finding about the gene and the disease.
cancer (continued). "While olaparib did not seem promising in this diverse group of cancer patients, it did show significant responses in BRCA1‐mutation carriers, due to the synthetic lethal combination of PARP inhibition and BRCA1‐deficiency." (PMID 28028012, 2017). "Thus, RAD52 has emerged as a target of interest for pharmaceutical intervention for novel synthetic lethal treatment strategies for BRCA1/2 mutant cancers." (PMID 29145865, 2017). "However, BRCA1/2-mutant cancer cells lack HR, and how these cells repair stalled replication forks has been an unresolved issue." (PMID 29145865, 2017). "In the case of ovarian cancer, which is the 7th most common cancer in women world-wide with an estimated age-standardised rate (ASR) of 6.3 per 100 000, it is known that germ line mutations in BRCA1 and BRCA2 increase the cancer risk in affected families dramatically." (PMID 28759630, 2017). "All mice injected with BRCA1-KO fibroblasts treated with cancer exosomes developed tumors." (PMID 28854931, 2017). "We identified no aberrant copy number changes in the HBOC cancer risk genes, including BRCA1 and BRCA2, by high resolution array CGH." (PMID 28435519, 2017). "Indeed, mutations within the BRCT repeats on BRCA1 disrupt its interaction with BRIP1 and lead to defects in DNA repair thereby resulting in several forms of cancers." (PMID 28968953, 2017). "In BRCA1/2 mutant cancers that have been treated with PARP inhibitors, increased expression of MDR1 genes have been observed, leading to increased expression of Pgp and a resultant higher rate of drug efflux, diminishing the therapeutic intracellular effect of PARP inhibitors." (PMID 28829366, 2017). "Normal cells will be able to repair these double strand breaks, in part through homologous recombination repair, however, BRCA-1/2 deficient cancer cells will not and thus will undergo chromosomal instability and apoptosis." (PMID 28008141, 2017). "In our hospital cohort, we detected one recurrent BRCA1 mutation (p.R1203X (c.3607C>T)) in one double cancer patient and in one OC patient without a family history, and the BRCA2 p.S1722fs (c.5164_5165 delAG) mutation was detected in two OC patients." (PMID 28961279, 2017). "Both genes play a crucial role in DNA repair processes, and the lack of functional BRCA1/2 proteins leads to loss of repair of DNA double-strand breaks and subsequently increases the risk of cancer." (PMID 29138528, 2017). "Loss-of-function mutations in the BRCA1 and BRCA2 genes increase the risk of cancer." (PMID 27452521, 2017). "For the first time we have shown that Plumbagin (PB), a naturally occurring naphthoquinone which is predominantly a ROS inducer, could reduce BCSCs specifically in BRCA1-defective, basal-like cancer cells." (PMID 27229859, 2016). "Although PD-L1 expression in tumor-infiltrating immune cells was different between HR-proficient and BRCA1/2-mutated tumors, PD-L1 expression in cancer cells was not different." (PMID 26871470, 2016). "However, BRCA1-methylated promoter in cancer tissues tended to be of a higher grade (82.4% methylated versus 69.6% unmethylated in grade 2 “tumors”)." (PMID 27413552, 2016). "BRCA1 inherited mutations in BRCA1 or BRCA2 predispose to breast, ovarian, and other cancers." (PMID 26885691, 2016). "The current germline BRCA1/2 testing strategy is mainly based on patients diagnosed with cancer." (PMID 27242959, 2016). "This case illustrates an increased sensitivity of BRCA1-mutated cancers to anthracycline therapies, irrespective of pathologic classification." (PMID 26918222, 2016). "Phosphorylation of BRCA1, γH2AX, Chk1 and Chk2 observed in cryptolepine treated cells is also supported by the evidences that have demonstrated that clinically used cancer chemotherapeutic agents which inhibit topoisomerase functions also activate these signaling cascade." (PMID 28009843, 2016).
cancer (continued). "As hypothesized, BRCA1-KO fibroblasts and HEK293 cells showed an uptake of cancer exosomes 3 to 13 times higher (6.6 +/− 0.6 times for BRCA1-KO fibroblasts and 7.7 +/− 2.0 for HEK293 cells) than that measured in control wild type fibroblasts." (PMID 27179759, 2016). "Our findings add an important new angle to this observation, showing that oncogenes can induce R-loops, which suggests that increased R-loop levels might also be common in cancer cells that are proficient in BRCA1 or BRCA2." (PMID 27725641, 2016). "The use of PARP enzyme inhibitors in cancer cells which are defective for BRCA1 and BRCA2, two proteins that localize the RAD51 recombinase to the sites of damaged DNA and promote HR repair, represent the best and most successful synthetic lethal approach in cancer therapy." (PMID 27884198, 2016). "The observed ages at diagnosis of BC in TH, SH1, and SH2, and the distributions of tumor characteristics may also reveal the interactions of BRCA1 and BRCA2 mutations, which may have implications for modeling the cancer susceptibility in TH." (PMID 27836010, 2016). "In concordance, inhibition of RAD52 DNA binding activity by small peptide aptamer exerted synthetic lethality in BRCA1 and BRCA2 mutated cancer cells and shRNA-mediated downregulation of RAD52 is lethal in tumor cell lines carrying BRCA2 inactivating mutations." (PMID 26784987, 2016). "In addition, treatment of cancers in mutation carriers has advanced with the development of PARP inhibitors, which take advantage of the loss of BRCA1/2 function in tumors." (PMID 27836010, 2016). "Thus, it is reasonable to speculate that SLFN11 epigenetic silencing compromises the correct partnership of DHX9 and BRCA1, and then it alters the correct function of the DNA damage response system, causing a shift in the platinum-associated chemosensitivity of the affected cancer cells." (PMID 26625211, 2016). "The BRCA1/2 carriers (mean±standard deviation: 46.6±8.5 years), especially BRCA2 (46.2±8.0 years), had an earlier onset age than non-carriers (50.7±10.3 years), which supports BRCA genes as potential cancer risk factors." (PMID 27257965, 2016). "The ability of BRCA1 protein to bind preferentially to topologically folded non-B DNA further hinted the value of these structures not only in transcriptional regulation, but also in processes leading to cancer development and senescence." (PMID 27277344, 2016). "Therefore, in this study we analyzed the ability of PB to target BCSCs from BRCA1-defective cancers." (PMID 27229859, 2016). "On the other hand, if testing for BRCA1 and BRCA2 focuses solely on unambiguously loss-of-function mutations with definitive effect on cancer risk, the cost per test may be markedly reduced." (PMID 26867194, 2016). "RNA was extracted from freshly isolated peripheral blood leukocytes of 58 cancer-free, female participants (22 BRCA1 mutation carriers and 36 non-carriers)." (PMID 27534398, 2016). "Our observations suggest that mutations in BRCA2 but not BRCA1 genes are linked with the initiation of the oncogenic process rather than with a clear role in the progression of the tumor or sensitivity to anti-cancer treatment." (PMID 27149669, 2016). "Accumulated evidence indicates that some individuals with BRCA1/2 germline variants can survive to an elderly age without developing cancer, while others never develop cancer." (PMID 26943589, 2016). "Recent evidence has revealed that some sporadic forms of cancers exhibit similar molecular, histological, and clinical phenotypes even in the absence of BRCA1/2 mutations, a defect known as ‘BRCAness,’ whose mechanism is not well understood." (PMID 27630665, 2016). "Moreover, it has been suggested that the expression of PARP1, γH2AX, BRCA1, and BRCA2 are closely associated with the progression of various human malignant tumors." (PMID 27643881, 2016). "In the tumor network, PVT1 competing for cancer related genes such as BRCA1, NOTCH2 and CDK1/4." (PMID 27580177, 2016).
cancer (continued). "These perturbations are associated with constitutive DNA damage response in nonmalignant cells of BRCA1/2 mutations carriers without cancer as well as in in vitro system." (PMID 26515461, 2016). "In most cell lines with intact DSB DNA repair mechanisms, treatment with PARP inhibitors at doses that successfully inhibit PARP activity does not cause cell death, providing an exquisite approach to specifically targeting cancer cells, especially those harboring mutant BRCA1 and BRCA2." (PMID 27705915, 2016). "Moreover, the bi-allelic inactivation of BRCA1 commonly observed in tumors of BRCA1 cancer patients results in early embryonic lethality when reproduced in animal models." (PMID 27259235, 2016). "Importantly, our data indicate that a treatment schedule in which a short Plk1 inhibition using BI2536 is performed before IR reduces the formation of BRCA1 and Rad51 foci, leading to impaired HR repair and to radiosensitization of cancer cells." (PMID 26745677, 2016). "Despite the critical roles of lncRNAs in developmental and tumorigenic regulation, their roles in BRCA1 function and its related diseases, in particular cancer, remain largely unknown." (PMID 27556296, 2016). "Although TNBCs from BRCA1 carriers less frequently express the AR, on multivariable analysis the factors that predicted >10% AR expression were older age and lower grade, whereas PD-L1 expression on cancer cells significantly predicted ⩾1% AR expression." (PMID 28721372, 2016). "We have demonstrated that FOXC1 can specifically identify BRCA1-mutant BLBC cancer." (PMID 27708239, 2016). "Overall, there is consistent evidence for activity of olaparib in BRCA1/2-related cancers." (PMID 27555886, 2016). "BRCA1 knockdown increased telomerase activity and the length of telomeres in cancer cells." (PMID 26515461, 2016). "These molecular processes could explain the relation between this SNP and BRCA1 or BRCA2 mutations, on cancer risk." (PMID 27015555, 2016). "BRCA1 overexpression caused shortening of telomeres in several cancer cell lines, independent of telomerase activity." (PMID 26515461, 2016). "As PALB2 functions together with BRCA1 and BRCA2, in the same DNA-damage response pathway, it has been thought plausible that PALB2 mutations, similar to BRCA1 and BRCA2 mutations, could predispose to other cancer types." (PMID 27099641, 2016). "Agilent design did not include one or more exons containing at least one cancer-linked mutation listed in COSMIC for 4 out of 112 genes (BRCA1, KMT2C, H3F3A, and SSX1) (data not shown)." (PMID 27578032, 2016). "The Counsyl Inherited Cancer Screen we have developed employs next-generation sequencing and includes comprehensive analysis of all coding exons of BRCA1 and BRCA2, 20 bp of flanking intronic sequences, and selected intronic and untranslated regions with known pathogenic variants." (PMID 27375968, 2016). "The absence of HR, which is a characteristic of BRCA1/BRCA2 deficient cancer cells, activates error-prone DSB mechanisms like non-homologous end joining (NHEJ) and results in genomic instability." (PMID 27532258, 2016). "Sporadic and BRCA1 basal-like cancers have grade independent miRNA expression profiles." (PMID 26152113, 2015). "Implementing our new streamlined microchip approach, we could directly visualize BRCA1 gene regulatory complexes from patient-derived cancer cells for the first time." (PMID 26395823, 2015). "We performed WGS on members of two cohorts of cancer genetics patients: those with BRCA1/2 mutations (n = 176) and those without (n = 82)." (PMID 26023681, 2015).
cancer (continued). "The tumors that develop in individuals with heterozygous BRCA1/2 mutations invariably lose their second BRCA1/2 allele, indicating that in certain cancers, the absence of BRCA1/2 is compatible with cellular proliferation." (PMID 25852742, 2015). "PTIP (Pax transactivation domain-interacting protein) was discovered as another phospho-53BP1 binding protein that is also required for 53BP1-mediated inhibition of BRCA1-directed HR and the sensitivity to poly ADP ribose polymerase (PARP) inhibitor in BRCA1 mutation cancer cells." (PMID 27462418, 2015). "Reduced cyclin D1 expression in BRCA1 basal cancers may, in part, be due to the inhibition of translation mediated by mir-576-3p, mir-1826 and mir-638." (PMID 26152113, 2015). "Since the prevalence of BRCA1/2 gene mutations in the general population is small not all familial clustering of cancers can be associated with mutations in these genes." (PMID 26236408, 2015). "Of the six proteins that were investigated via immunohistochemistry, four (cyclin D1, FOXP1, NRP1 and CD99) showed reduced expression in BRCA1 cancers in the initial cohort with reduced expression for FOXP1, cyclin D1 and NRP1 subsequently confirmed in the validation cohort." (PMID 26152113, 2015). "Therefore, olaparib is now licensed for BRCA1/2 mutant cancers and steps are being taken to identify additional predictive biomarkers, including other known homologous recombination defects." (PMID 26557500, 2015). "From this knowledge, research on BRCA1/2 pathways and their impact in other cancers has evolved." (PMID 26236408, 2015). "In addition, expression of Ku 70 and Ku 80 is highly dependent on the genotype of the cancer such as BRCA1, HER2 and RAD51 status." (PMID 26252900, 2015). "Polyploidy in cancer cells could lead to the overexpression of BRCA1, p19arf and other DNA repair genes in FEN1 mutant cells." (PMID 26668074, 2015). "However, BRCA1 or BRCA2 are not only inactivated through gene mutation, also DNA hypermethylation of the genes is frequently reported for several cancers." (PMID 25852742, 2015). "Within the “BRCA1” cluster there was a subgroup composed entirely of 10 BRCA1 cancers." (PMID 26152113, 2015). "TNBC tumors have the poorest prognosis and tend to grow and spread to other parts faster than other cancers and often harbor BRCA1 mutations or lack of expression." (PMID 25583261, 2015). "These genes can also be involved in the development of non-hereditary tumours as somatic BRCA1/2 pathogenic variants are found in some of these cancers." (PMID 25859162, 2015). "Regarding BRCA1 associated cancer cases neither TRα nor TRβ presented a significant association to any of the clinicopathological variables examined." (PMID 26029931, 2015). "Nevertheless, our findings suggest immunohistochemistry for FOXP1/NRP1/cyclin D1 may be useful, in conjunction with family history, in selecting patients with basal cancers for BRCA1 screening." (PMID 26152113, 2015). "BRCA1 basal cancers, when compared to sporadic basal cancers showed reduced positivity for FOXP1 (6/20 [30 %] vs. 37/49 [76 %], p < 0.001), cyclin D1 (8/22 [36 %] vs. 30/46 [65 %], p = 0.025), NRP1 (2/20 [10 %] vs. 23/46 [50 %], p = 0.002) and CD99 (17/20 [85 %] vs. 7/19 [37 %], p = 0.002)." (PMID 26152113, 2015). "Using functional assays including proliferation rate, ɣ-irradiation sensitivity and genomic instability, we demonstrate that BRCA1 VUS/mutations have a spectrum of phenotypes, suggesting that both deleterious mutations and VUS impart relative degrees of risk for cancer development." (PMID 26246475, 2015). "Our hypothesis was that these miRNAs could impede DNA damage repair by reducing BRCA1/2 expression, thereby increasing the sensitivity of cancer cells to chemotherapy." (PMID 25537514, 2015).
cancer (continued). "Although experimental evidence explaining the impact of TRs in BRCA1 associated cancers is still lacking, the current study showed TRβ to be more frequently expressed in BRCA1 mutation carriers." (PMID 26029931, 2015). "Basal cell lines, all with wild-type BRCA1, had a profile more closely resembling sporadic basal cancers rather than basal cancers with known BRCA1 mutations." (PMID 26152113, 2015). "Cancers without BRCA1 or BRCA2 loss but with accumulation of similar genomic scars also show increased sensitivity to platinum-based chemotherapy." (PMID 26015868, 2015). "BRCA1 mutation-positive carriers were identified among all subtypes except for undifferentiated adenocarcinomas, whereas BRCA2 mutation-positive cases were identified among the serous and undifferentiated adenocarcinoma subtype cancers." (PMID 25884701, 2015). "It is worth noting that although LOH in cases with BRCA1 and BRCA2 truncations mutations were largely restricted to OV and BRCA, the majority of LOH truncations in other genes (for example, ATM, PALB2, BAP1, FANCM) were found across cancer types." (PMID 26689913, 2015). "The mechanisms by which BRCA1/2 mutations lead to cancer of the breast and ovaries are not fully understood." (PMID 26236408, 2015). "In conclusion, we showed that multiplex PCR followed by NGS is useful for screening BRCA1 and BRCA2 germline mutations of probands and could be applicable to cancer prevention in unaffected relatives carrying the same mutation." (PMID 25802882, 2015). "Autoantibodies to proteins involving in the synthetic lethal interaction (PARP1 and BRCA1/2) might act as potential biomarkers for diagnosis of cancer." (PMID 25865228, 2015). "Compared with sporadic basal cancers, BRCA1 cancers showed reduced positivity for proteins predicted to be regulated by miRNAs: FOXP1 (6/20[30 %] vs. 37/49[76 %], p < 0.001), cyclin D1 (8/22[36 %] vs. 30/46[65 %], p = 0.025), NRP1 (2/20[10 %] vs. 23/46[50 %], p = 0.002)." (PMID 26152113, 2015). "In addition, recent evidence suggests that heterozygous BRCA1 mutant cells have an exaggerated response to estrogen induced DNA damage, providing a possible explanation of the cancer tissue specificity seen in BRCA carriers." (PMID 26246475, 2015). "There was one interval cancer in a BRCA1 carrier which was lymph node positive and >2 cm." (PMID 25741458, 2015). "The reason why the patients with defective BRCA1/2 have a longer survival times compared with BRCA1/2 wild-type carcinomas is related with BRCA1/2-defects in cells making them more sensitive to conventional chemotherapy, especially to the platinum-based chemotherapy." (PMID 25823848, 2015). "Additionally, BRCA1 and 15 other important cancer –related genes were found to be differentially expressed in WBC from patients and carriers as compared to controls." (PMID 25403427, 2014). "Surprisingly, BRCA1 induces the transcription of ESR1 which encodes ERα, and the positive feedback between BRCA1 and ERα provides a rational explanation for why many BRCA1 negative cancers are ERα negative." (PMID 24860786, 2014). "For simplification, we termed cancer-free females harboring methylated BRCA1 as “Carriers”." (PMID 25403427, 2014). "In addition, we identified 13 cancer-free healthy females (9.1%) harboring methylated BRCA1 promoter in their WBC." (PMID 25403427, 2014). "However, the fact that most of them were also BRCA1-mutant cases has so far prevented us to demonstrate a direct link between cancer and reduced expression of the gene." (PMID 24475217, 2014).